RNU6-480P (RNA, U6 small nuclear 480, pseudogene)
Gene: Small nuclear RNA gene on chromosome 5 (51,055,353 to 51,055,459, reverse strand). Ensembl gene ENSG00000207060.
Homologues: Orthologues: macaque U6 (97% identical), chimpanzee U6 (96% identical), rat LOC120102573 (88% identical), pig U6 (87% identical), guinea pig U6 (82% identical). Paralogues in human: RNU6-16P (94% identical), RNU6-46P (94% identical), RNU6-1 (93% identical), RNU6-2 (93% identical), RNU6-39P (93% identical), RNU6-3P (93% identical), RNU6-4P (93% identical), RNU6-5P (93% identical), RNU6-6P (93% identical), RNU6-9 (93% identical), RNU6-12P (93% identical), RNU6-13P (93% identical), and 1287 more.